MMP2 (matrix metallopeptidase 2)
Diseases named in the same sentence as MMP2 in open-access papers (continued):
Sharing a sentence is not in itself a finding about the gene and the disease.
tumor (continued). "Likewise, the TME acidic pH provokes changes in tumor cells’ morphology and MMPs’ expression; for instance, the formation of tumor cell filopodia and invadopodia with a rise in pro-MMP-2 and cathepsin B in these cell structures." (PMID 35720130, 2022). "MMP-1, MMP-2, MMP-8, MMP-11, and MMP-13 are implicated in the regulation of tumor cell migration." (PMID 36776395, 2022). "Decreased tumor cell viability and proliferation, as well as collagen I-mediated cell adhesion and the action of MMP-2 and MMP-9, enzymes that play an important role in the degradation of the extracellular matrix and promote tumor invasion and metastasis, have been reported." (PMID 35563133, 2022). "N-acetylated MMP-2 becomes stabilized, thereby promoting cell invasiveness and tumor metastasis." (PMID 36433943, 2022). "Homoplastically, MMP2 induces tumor neovascularization through the activation of pro-angiogenic factors such as vascular endothelial growth factor (VEGF) and TGF-β, and it also promotes the proteolytic degradation of extracellular proteins to drive tumor metastasis." (PMID 36324128, 2022). "Accordingly, extracellular Hsp90α could stabilize MMP-2 and protect it from degradation in tumor cells." (PMID 35847880, 2022). "MMP2 promotes the lysis of fibronectin (FN) and vitronectin (VN), thereby enhancing the adhesion of protein hydrolytic fragments with adhesive properties; it triggers tumor metastasis due to its involvement in the adhesion of tumor cells to mesothelial cells." (PMID 36147444, 2022). "When MMP2 was secreted by tumor cells, Cy3 emission at 580 nm could be recovered upon MMP2-responsive Pep-QSY7 cleavage." (PMID 34991595, 2022). "Thus, restraining the secretion of MMP2 and CAFs activation inducers by tumour cells, cabozantinib would avoid the release by CAFs of pro–motility (SDF1) or ECM remodelling-stimulating (HGF) factors." (PMID 35106125, 2022). "Furthermore, MT1-MMP is an important activator of MMP2 leading to an enhanced invasion and progression in different tumor types including GBM." (PMID 35682709, 2022). "The tumor-promoting functions of tumoral and stromal MMP-2 have also been demonstrated." (PMID 36741729, 2022). "Matrix Metalloproteinase-2 (MMP-2) is a protease involved in ECM degradation in tumours." (PMID 36195696, 2022). "MMP-2 can digest tumor extracellular matrix, creating a pathway for tumor cell metastasis." (PMID 35535313, 2022). "Therefore, restraining the MMP-9 and MMP-2 expression is an effective strategy for tumor metastasis treatment." (PMID 35954126, 2022). "Growing in such a hostile environment (acidosis, hypoxia), tumor and stromal cells may also overexpress some specific enzymes, including MMP-2, MMP-9, FAP-α, legumain, uPA, and some elastases." (PMID 35845404, 2022). "Moreover, in the circBRWD3 overexpression tumor model, E-cadherin was upregulated, while N-cadherin, Vimentin, MMP2, and MMP9 were downregulated." (PMID 36443711, 2022). "Therefore, PLGLAG is the restriction site of MMP-2, and is a widely used linker, which can release the modified drug in tumour tissue." (PMID 36195696, 2022). "Enhanced expression of MMP2/9 in exosomes from prostate cancer is correlated to tumour progression." (PMID 35158891, 2022). "MMP2 and MMP9 activation has been implicated in tumor invasion and metastasis in GC." (PMID 35705840, 2022). "The role of MMP-2 substrate is to allow for specific cleavage at tumor sites." (PMID 35744957, 2022). "As a result, dual‐targeting MMP‐2 and TfR1 improved the accuracy of tumor targeted therapy." (PMID 35600646, 2022). "These MMP-sensitive micelles enter the tumor microenvironment as a result of enhanced permeability and retention effects, where they are disrupted due to an increased MMP-2 enzyme in the tumor site, thus releasing the antibody and the inhibitor in a controlled manner." (PMID 36145608, 2022). "Both MMP-2 and MMP-9 are associated with tumor invasion, metastasis and angiogenesis." (PMID 36016565, 2022).
tumor (continued). "Meanwhile, anti‐PD‐1 antibodies were released in the tumor microenvironment in response to MMP‐2." (PMID 35652198, 2022). "As we discuss, activating β-ARs may result in anti-tumor effect (upregulate Cx43 protein levels) or pro-tumor effect (upregulate MMP-2 and MMP-9 levels)." (PMID 36010960, 2022). "In addition, IHC analysis revealed that fewer Ki-67-positive and MMP2-positive cells were observed in the tumor sections from the miR-30c-5p-EV group than in NC-EV group." (PMID 34991623, 2022). "Furthermore, the expressions of HIF-1α and its downstream metastasis-associated proteins including MMP-2 and VEGF in tumor sites were notably inhibited." (PMID 35893790, 2022). "Further, analysis of TCGA database identified high MMP2 expression in tumor tissues." (PMID 35901491, 2022). "Reliance of MMP2 on eHsp90 is not only important for tumor cell invasion but also for angiogenesis." (PMID 36060252, 2022). "Among all members of the MMP gene family, MMP-2 and MMP-9 are considered to be especially important in the degradation of the extracellular matrix that is associated with malignant behavior in a variety of tumor cells." (PMID 35163891, 2022). "MMP2 and MMP9 was highly associated with primary tumor status (T)." (PMID 35449123, 2022). "Given the fact that miRNAs can mediate ECM remodelling via MMP2, a process that drives tumour invasion, it may be possible that these miRNAs influence myopic scleral ECM remodelling in a similar way during visual manipulation in form‐deprivation myopia." (PMID 34841657, 2022). "In glioblastomas, αvβ3 and αvβ5 are upregulated, and αvβ3 co-localizes with MMP-2 in tumor cells." (PMID 35204054, 2022). "Indeed, tumor cells attenuate the immune anti-tumoral action by MMP-2, MMP-9, MMP-13, and MMP-14 secretion, leading to T-cell activity hindrance." (PMID 35572966, 2022). "Furthermore, PTC patients with high preoperative serum levels of MMP-2 are characterized by a larger tumor size, presence of lymph node metastasis, extrathyroidal invasion and an advanced TNM stage." (PMID 36077709, 2022). "Previously, we have reported the development of a novel polymer P-DOX-iRGD and demonstrated that the covalent conjugation of the iRGD peptide via MMP2-sensitive bonds enhanced the accumulation and penetration of the polymeric conjugate into tumor cell monolayers and spheroids." (PMID 36015351, 2022). "These constructs exhibited an increased expression of markers of tumor invasion and drug resistance (matrix metalloproteinase-2 and -9 [MMP2, MMP9], vascular endothelial growth factor receptor-2 [VEGFR2], and O6-methylguanine-DNA methyltransferase [MGMT]) when compared to solely U118-printed fibers." (PMID 35804898, 2022). "Moreover, the mRNA expression of miR-497/ NFkB1 /Ki67/ CD147/MMP-2 pathway in tumor were measured by RT-qPCR." (PMID 35896012, 2022). "Lgmn is a lysosomal cysteine protease, which is involved in extracellular matrix remodeling by degrading fibronectin and regulating the activity of matrix metalloproteinases (MMPs), especially MMP-2, as well as protecting against apoptosis and facilitating tumor growth and invasiveness." (PMID 36232358, 2022). "Matrix metalloproteinases (MMPs), mainly including MMP-2 and MMP-9, which are overexpressed in the tumor microenvironment, have long been closely implicated in tumor invasion and metastasis and can be applied as stimuli for the design of bio-responsive materials." (PMID 35845404, 2022). "VIP/VIPR1 signaling maintained tumor proliferation and invasiveness by upregulating the expression of cyclins and angiogenic factors, including cyclin D1, MMP-2/MMP-9, VEGF, and COX-2, as well as stimulating tumor growth through the activation of PKA/ERK1/2 pathway." (PMID 35864952, 2022). "Indeed, PTTG1 contributes to the metastatic process and tumor progression through the transactivation of many targets, such as matrix metalloproteinase 2 (MMP-2)." (PMID 36230799, 2022).
tumor (continued). "Specifically, PDOs have lower levels of several factors (including B-cell lymphoma 2/Bcl-2, MMP2, Cathepsin D and Survivin) as compared to CTCDOs, suggesting that proteins related to tumor cell survival and aggressiveness increase during sequential stages of the disease." (PMID 35260172, 2022). "There is, however, the inhibition of MMP2 that could result in the activation of the FAK signaling pathway or the tumor microenvironment pathway." (PMID 36009530, 2022). "In NSCLC cells, except that increased MMP2/14 could degrade the extracellular matrix and enable tumor cells to invade into the area nearby, it also provided the opportunity to transactivate EGFR." (PMID 35013118, 2022). "The effect of DCH on tumour growth in tumour-bearing mice was explored in in vivo experiments, and the expression of MMP2 and MMP9 and EMT correlation indexes was measured by immunofluorescence and WB, and the changes in cytoskeletal F-actin and β-tubulin were measured by fluorescence." (PMID 36408277, 2022). "DCP is implicated in tumor angiogenesis and rising genetic expression of angiogenic factors like vascular endothelial growth factor (VEGF), endothelial growth factor-receptor (EGF-R), and matrix metalloproteinase-2 (MMP-2)." (PMID 35547447, 2022). "Given the importance of these mechanisms, we investigated whether hsa-miR-30a-3p functions as a tumor-suppressor miRNA through MMP2 and MMP9 suppression in BC." (PMID 35449123, 2022). "MMP2 and MMP-9 are associated with tumor invasion and metastasis, and the concentration of these biomarkers differs significantly in the saliva of healthy individuals, patients with premalignant diseases of the oral cavity, and OSCC patients, suggesting their diagnostic and prognostic role." (PMID 36412636, 2022). "Furthermore, GAMs were capable of augmenting the secretion several genes like Vegfa and Hgf which implicated in angiogenesis, ARG1 and Tgfb3 which are implicated in immune suppression, and MMP2, MMP14, and Ctgf which are implicated in tumor invasion." (PMID 35419058, 2022). "Since MMP2 is important for extracellular matrix digestion, we speculate that tumor cells promote fibroblast to secret matrix digestion products to facilitate metastasis." (PMID 35464471, 2022). "In the TNBC microenvironment, the “two-in-one” ILips facilitated the MMP2-responsive release of aCD47 to efficiently polarize the M2 macrophages toward the M1 phenotype to enhance the phagocytosis of tumor cells and activate the systemic T-cell immune response." (PMID 36159668, 2022). "Knockdown of MUC15 in HOS and U-2OS could promote tumor cell apoptosis, down-regulate the expression of MMP2/9, reduce the epithelial interstitial transition and silence the Wnt/b-Catenin signal pathway." (PMID 33391443, 2021). "mEHT could support the intratumoral attraction of distantly injected NK-cells, contributed by CXCL11 and MMP2 upregulation, resulting in an additive tumor destruction and growth inhibition." (PMID 33732640, 2021). "In addition, a significantly larger peripheral area expressing MMP-2 was noted at 63 dpt in DH82-UV-CDVai neoplasms compared to untreated controls (p = 0.0017) and DH82-medium xenografts (p = 0.0038)." (PMID 33808256, 2021). "Intriguingly, through injecting KYSE-30 cells with OV-TEAD4 transfection or in combination with shRNA-SGK1 transfection into nude mice, we found that SGK1 silencing markedly interfered with the effects of TEAD4 overexpression on tumor volume and the expression of Ki67 and MMPs (MMP2 and MMP9)." (PMID 33517828, 2021).
tumor (continued). "Moreover, Bai was tested in a pancreatic neuroendocrine tumor cell line (BON1 cells), and the observed reduction of tumor migration and invasion related to the decreased MMP-2 and MMP-9." (PMID 33498927, 2021). "Subsequently, tumor metastasis-related proteins MMP-2 and MMP-9 were determined." (PMID 34539408, 2021). "By comparing quantitative information perturbed by MMP2 KD and the proteomic expressional change according to tumor, node, and metastasis (TNM) stage, we suggest that increased metastatic feature of CRC during progression from stage I to II is the result of focal adhesion kinase (FAK) activation." (PMID 34429501, 2021). "Indeed, MMP2 (and other MMPs) has been found in exosomes derived from immune, tumor and stromal cells in the TME." (PMID 34032639, 2021). "Therefore, the development of MMP-2-sensitive tumor-imaging probes and delivery systems has previously been undertaken for cancer-specific therapeutics." (PMID 34078185, 2021). "We thus examined the expression of MMP2 in shNT and shOrai3 tumor lysates." (PMID 34885048, 2021). "Thus, while F1 tumor cells express MMP2, they lack the ability to respond to TLR activation or MMP2 stimulation." (PMID 34032639, 2021). "Indeed, PTTG1 contributes to the metastatic process and tumor progression by transactivation of matrix metalloproteinase-2 (MMP-2)." (PMID 33430117, 2021). "Moreover, pretreatment with MMP-2 increased nanocomplex tumor permeability, and western blot showed that HA-P-PEI/PD-L1–siRNA efficiently downregulated the PD-L1 expression in H1975 cells." (PMID 34078185, 2021). "There was, however, a higher tumor incidence in Mmp2-OE tumors." (PMID 34032639, 2021). "Similarly, MT1-MMP is an essential substance in MMP2 activation and is highly expressed in the periphery of the tumor." (PMID 34007838, 2021). "Hypoxia-induced NF-κB also up-regulates cyclooxygenase-2 (COX-2) and consequently the expression of some essential cell surface and cytoskeletal proteins required for tumor invasion, including matrix metalloproteinase-2 (MMP-2) and urokinase-type plasminogen activator (uPA)." (PMID 34639215, 2021). "It is also possible that tumor cells release full length MMP2 as they undergo necrosis." (PMID 34032639, 2021). "Additionally, the γ2 chain synergistically contributes to the formation of budding tumor cells with MMP-2, and the level of γ2 chain expression in the submucosal and subserosal invasive fronts was an independent prognostic factor." (PMID 34502094, 2021). "Moreover, the expression of MMP2 and MMP9, tumor metastasis-associated molecules, were reduced after silencing CD151 expression." (PMID 34108040, 2021). "The core of NPs contained a peptide (VPLGVRTK) responsive to tumor‐derived MMP‐2." (PMID 34105297, 2021). "Moreover, researchers have utilized nanoparticles to apply MMP2 enzyme activity to reduce ECM deposition in the tumor microenvironment, which results in the enhancement of immune infiltration." (PMID 34121340, 2021). "What we investigated was whether the detected MMP2 expression had a relationship with the tumor invasion." (PMID 34976953, 2021). "In endometrial cancer (EC) VEGF and MMPs play a major role in tumor growth and metastasis since MMP-2 and -9 are persistently upregulated in EC although the expression levels are closely associated with the clinical stage, tumor invasion, and metastasis of the disease." (PMID 34912809, 2021). "To explore the anti-tumor effect of ProIFN, we first determined the expression levels of tumor-enriched enzymes such as MMP-2, MMP-9, MMP-11, MMP-14, fibroblast activation protein alpha (FAP), and urokinase plasminogen activator (uPA) in a variety of tumor lines." (PMID 34620867, 2021). "It has also been reported that MMP2 played a crutial role in tumor invasion and metastasis." (PMID 34976953, 2021). "Depletion of Mmp2 in B16 cells reduces tumor growth and promotes T cell proliferation in the TME." (PMID 34032639, 2021).
tumor (continued). "In conclusion, the present study demonstrated that the OSCC invasive subtype SCC stromal cell xenograft promoted the higher localization of BMDCs to the invasive front line of the tumor and the expression of MMP2 compared to the less-invasive subtype—the VSCC stromal cell xenograft." (PMID 35008304, 2021). "Researchers have therefore proposed the targeting of MMP-2 in the management of tumor metastasis." (PMID 34445345, 2021). "This could represent an additional way of regulating MMP2 activity in the context of tumor establishment and progression." (PMID 34032639, 2021). "Moreover, the MMP-2 and IL-8 levels were significantly higher in tumor tissue vs. control (p < 0.001)." (PMID 33846436, 2021). "MiR-20b-5p might act as a tumor inhibitor by impeding MMP-2 expression leading to cell cycle arrest as well as regulative function on oxygen balance." (PMID 34076696, 2021). "As elevated level of MMP-2 promotes tumor progression and metastatic ability, the secretory proteins regulated by MMP-2 also could reflect the pathological status of cancer cell and be secreted to plasma proteome of CRC patients." (PMID 34429501, 2021). "Resveratrol may also downregulate the expression of MMP-2 in hepatoma in nude mice through the NF-κB pathway to inhibit tumor growth and invasion ability." (PMID 33578780, 2021). "MiR-21 overexpression in stromal fibroblasts induces TGF-β-dependent fibroblast-to-myofibroblast trans-differentiation and negatively controls RECK protein expression, which regulate negatively MMP2 via post-transcriptional mechanisms, then enhanced tumor invasion through upregulated MMP2 activity." (PMID 33562604, 2021). "Furthermore, MMP2 was upregulated in GC and MMP2 overexpression reversed the anti-tumor response of circ_0000620 knockdown in GC progression." (PMID 34972532, 2021). "Similarly, increased expression of MMP-2 was observed in muscle-invasive pT2 < or = bladder tumours than in pT1a tumours." (PMID 33923108, 2021). "Indeed, Mmp2 overexpression in B16 cells potentiated rapid tumor growth, which was accompanied by reduced intratumoral cytolytic cells and increased M2 macrophages." (PMID 34032639, 2021). "Accelerated tumor growth in Mmp2-OE cells partially depends on cDC1s and lymphoid cells." (PMID 34032639, 2021). "MMP-2 is one of MMPs, which are overexpressed in a variety of tumor cells." (PMID 34796163, 2021). "In addition, the selection pressure when subjected to hypoxia leads to the survival of more malignant subpopulations of tumor cells expressing MMP-2, MMP-9, and VEGF." (PMID 34194604, 2021). "Together with our data, we hypothesized that MMP-2 also enhances the migration ability of CRC tumor cells by modulating the composition of the secretome." (PMID 34429501, 2021). "MMP2 and MMP9 were markers closely associated with tumor invasion and metastases." (PMID 34479497, 2021). "Selenite inhibits the invasion of tumor cells via decreasing expression of MMP-2, MMP-9, and uPA." (PMID 34065478, 2021). "USP22 enhanced both MMP2/9 expression, the tumour invasive markers." (PMID 34226501, 2021). "Similar to the findings in vitro, MMP-2 was notably decreased in the MUC3A-knockdown tumor." (PMID 34326691, 2021). "It promotes tumor cell invasiveness through increased MMP-2 activity and E-cadherin suppression." (PMID 34445544, 2021). "We theorized that MMP2 would skew T cells toward a Th2 phenotype and potentiate tumor growth." (PMID 34032639, 2021). "In addition, bax, bcl-2, MMP-2, caspase-3 and p-glycoprotein were regulated by CK-M to promote tumor cell apoptosis and inhibit tumor cell invasion, metastasis, and outflow." (PMID 34654430, 2021).